MITF (melanocyte inducing transcription factor)
Diseases named in the same sentence as MITF in open-access papers (continued):
Sharing a sentence is not in itself a finding about the gene and the disease.
melanoma (continued). "NRP1 is a transmembrane glycoprotein that has been shown to affect IFNγ signaling in endothelial cells, and is furthermore negatively regulated by MITF in melanoma cells." (PMID 39736644, 2024). "Through these opposing mechanisms, oncogenic BRAF-V600 ensures that MITF protein levels are permissive for melanoma cell survival and proliferation." (PMID 38472212, 2024). "miR-211 is a transcriptional target of MITF in melanotic melanoma cells that targets ER degradation-enhancing alpha-mannosidase-like 1 (EDEM1) of tyrosinase through the ER-associated degradation (ERAD) pathway." (PMID 38672652, 2024). "On transcriptome level, SK-Mel-28 dr cells showed elevated AXL and reduced MITF expression, representing a trend towards an AXLhigh/MITFlow phenotype, which defines a dedifferentiated melanoma phenotype." (PMID 39835134, 2024). "Based on this, the slow-proliferative melanoma cell state is characterized by a low level of the lineage-specific transcription factor MITF." (PMID 39398277, 2024). "MITF is significantly involved in the regulation of multiple biological processes, including melanoma differentiation, proliferation, migration, and senescence." (PMID 38275910, 2024). "8-oxoG levels were significantly lower in zebrafish melanoma tumors overexpressing MITF compared with control tumors." (PMID 39277608, 2024). "ACLY promotes MITF-PGC1α axis transcription by increasing histone acetylation of the MITF locus, making melanoma resistant to MAPK inhibitors." (PMID 39609317, 2024). "•AXL+ and/or MITF+ melanoma subpopulations were analyzed by NanoString, scRNAseq and multiplex immunofluorescence." (PMID 39697983, 2024). "Expression levels of most of the redox-related genes were highly correlated with MITF across melanoma cell lines and patient tumor samples, accentuating the robustness of the MITF-driven redox program in melanoma." (PMID 39277608, 2024). "Altogether these data confirm the importance of the down-modulation of the MITF/miR-579-3p axis in the development of resistance to targeted therapies in melanoma." (PMID 38472212, 2024). "These diverse effects across different melanoma types underscore the complexity of MITF-related activities among various types of MM, aiding the development of a more effective understanding of MMs’ pathophysiology as well as their targeted therapies." (PMID 38254754, 2024). "The effects of the Mitfmi-sl mutation on protein stability were investigated by expressing Flag-tagged (at C-end) MITF-WT, MITF-sp, and MITF-sl proteins in a doxycycline (dox)-inducible vector transfected into A375P melanoma cells." (PMID 39169200, 2024). "Altogether these data confirm the previous findings where we showed that miR-579-3p expression levels mirror those of MITF protein in melanoma cells." (PMID 38472212, 2024). "In 15% to 20% of MM cases, the amplification and over-expression of MITF leading to bona fide melanoma oncogenes have been found." (PMID 38254754, 2024). "The search terms “melanoma”, “mutation”, “surgery”, and “metastatic melanoma” and specific gene names (TMB, BRAF, NRAS, EGFR, c-KIT, MITF, etc.)were used in combination with the Boolean operators AND or OR." (PMID 38534309, 2024). "Melanocortin 1 receptor (MC1-R) is expressed mainly in melanocytes, and the MC1R/cAMP/MITF axis plays an important role in the growth, survival and differentiation of melanocytes and melanoma cells." (PMID 38351314, 2024). "Cells expressing at least one melanoma lineage marker (MITF, PRAME or the melanocyte differentiation antigens) and negative for CD45 were considered melanoma cells." (PMID 39697983, 2024). "It has even been shown that β-catenin itself is a regulator, as is the MAPK pathway acting on MITF, which is fundamental in controlling cell proliferation, survival, and differentiation in melanoma." (PMID 39594467, 2024).
melanoma (continued). "MITF target genes play important roles in melanoma survival, including inducing an increase in the expression of the antiapoptotic gene Bcl2, cell cycle-related gene CDK2, cell motility-related gene c-Met, and pigment production/secretion-related gene RAB27A." (PMID 39684511, 2024). "Although numerous studies have explained the roles of MITF in melanocytes and in melanoma development, the function of MITF in the hematopoietic or immune system—beyond its function in melanin-producing cells—is not yet fully understood." (PMID 38351314, 2024). "MiRNAs like miR‐211‐5p‐5p promote glycolysis in melanoma cells, while others are involved in MITF downregulation, such as miR‐137." (PMID 39494561, 2024). "Dox-inducible A375P melanoma cells expressing MITF-WT, MITF-sp, and MITF-sl were exposed to CHX and the nuclear export inhibitor leptomycin B (LMB) for different time points before harvesting for Western blotting." (PMID 39169200, 2024). "Taken together, these data suggest that 50 EtOH and 95 EtOH can alleviate melanogenesis in human melanoma cells with inhibitory effects against MITF, TYR, TRP-1, and MC1R mRNA expression." (PMID 39335872, 2024). "When overexpressed in the 501Mel and SKmel28 melanoma cell lines (which express high levels of MITF), the MITF-sl protein was also less stable than the MITF-WT and MITF-sp proteins, regardless of the S73 phosphorylation status." (PMID 39169200, 2024). "This indicates an analogous sensitivity profile of MITF or AXL melanoma cells to both targeted and immunotherapy." (PMID 39697983, 2024). "In brief, at peak MITF levels, melanoma cells express differentiation genes, promoting a pigmented phenotype and terminal differentiation." (PMID 39562548, 2024). "Alternatively, T-cell-secreted pro-inflammatory cytokines have been reported to promote dedifferentiation of melanoma cells by suppressing MITF expression, explaining why more infiltrated tumors have reduced numbers of MITF+ cells." (PMID 39697983, 2024). "Concerning MITF, a positive feedback loop at the gene level between this TF and AC in the context of melanoma phenotype switching has been previously observed." (PMID 39136013, 2024). "Previously, MITF was shown to be a key gene regulator involved in melanocyte and melanoma cell functions, affecting skin color regulation, melanoma growth, immunity and melanoma progression." (PMID 38351314, 2024). "We have demonstrated that PANX1 influences the regulation of effector molecules that control melanocyte differentiation (e.g., MITF and β‐catenin) and the metabolism of melanoma cells." (PMID 38327091, 2024). "In human melanoma tissue samples, we likewise detected a wide range of MITF expression levels while in healthy tissue samples the levels were consistently low." (PMID 39562548, 2024). "Changes associated with MITF and AXL expression patterns in melanoma cells were proposed as means for cells to withstand therapeutic effects by transitioning from one differentiation state to another, which is often referred to as phenotypic switching." (PMID 38672652, 2024). "Dedifferentiation of melanoma cells was induced via either siRNA or shRNA mediated MITF knockdown and the cells were subsequently treated with IFNγ." (PMID 39736644, 2024). "We also observed that miR-579-3p and MITF are positively correlated in BRAF-mutant melanoma cell lines." (PMID 38472212, 2024). "In melanoma, TERT promoter mutations, MITF, and CTNNB1 were amongst the genes enriched in metastatic vs. primary Class 1 BRAF mutant tumors." (PMID 38275886, 2024). "In melanoma, MITF expression affects the recruitment of immune cells, including T cells, B cells, natural killer (NK) cells and myeloid cells, by altering the levels of chemokines and cytokines and ultimately altering therapeutic efficacy." (PMID 38351314, 2024). "Nevertheless, the role of β-Catenin and MITF in cancer and melanoma remains incompletely understood." (PMID 39562548, 2024).
melanoma (continued). "Our study suggests that 10E-PDA can inhibit melanogenesis in B16F10 melanoma cells by blocking MITF nuclear translocation and reducing downstream melanogenesis factors such as tyrosinase and TRP-1 at both the mRNA and protein levels." (PMID 39765875, 2024). "Our results suggest that MITF directs a transcriptional program that protects melanoma cells from oxidative stress in vitro." (PMID 39277608, 2024). "Several intrinsic tumor cell states have been suggested for melanoma, which generally align on a gradient of MITF-low to MITF-high expression levels." (PMID 38594286, 2024). "In this study, the results revealed a significant increase in the expression of the genes of CDH1 and MITF in AM, which strongly correlates with poor immunity in patients with melanoma." (PMID 38469735, 2024). "Recent discoveries have revealed a physical interaction between CREB and β-catenin upon PKA/cAMP pathway activation in normal human melanocytes and B16-F0 mouse melanoma cells, resulting in functional cooperation on the MITF promoter." (PMID 38920996, 2024). "In male melanoma, AR-positive patients exhibited worse survival rates compared to AR-negative patients, attributed to the ability of AR to enhance melanoma cell invasion through modulation of the MITF-AXL signaling pathway." (PMID 39597836, 2024). "As a consequence, MITF expression levels are balanced to allow survival and proliferation of melanoma cells because too high levels of MITF stimulate differentiation and block of proliferation." (PMID 38472212, 2024). "We next examined bulk RNA-Seq data from TCGA melanoma tumor samples (n = 473), and the relationship between the proliferative, invasive, Epgn1, and Epgn3 signatures with MITF and ITGA3." (PMID 38319712, 2024). "By promoting mRNA translation, DDX3X can increase MITF protein levels and alter metastatic potential and response to targeted melanoma therapies." (PMID 38539466, 2024). "PRDX1 shows significant co-expression with MITF in melanoma patients, with PRDX2 showing a tendency towards mutual exclusivity." (PMID 38790661, 2024). "Mutated BRAF exerts exquisite control over MITF, which regulates the expression of key cell cycle facilitators, such as CDK2 and CDK4, stimulating melanoma cell proliferation, survival, and phenotype switching from proliferative and invasive states." (PMID 39735251, 2024). "RES reduced the expression of melanogenesis-related proteins, such as tyrosinase, tyrosinase-related protein 1 (TYRP1), TYRP2, and MITF in melanoma cells." (PMID 39337478, 2024). "Low MITF activity is especially crucial for individuals with melanoma because it is predictive of early resistance to targeted melanoma therapies." (PMID 39092608, 2024). "BMAL1 also transcriptionally regulates MiTF in human melanoma cells to influence melanin synthesis against UVB irradiation." (PMID 38245503, 2024). "In sum, the majority of melanoma lines with high MITF levels responded with a reduction in invasion and proliferation after either TPC2 or Rab7a KD/KO." (PMID 39562548, 2024). "This is of utmost interest given that MITF functions are essential for melanocytic lineage commitment and to govern the balance between melanoma cell proliferation and differentiation." (PMID 38472212, 2024). "Next, we investigated the relationship between the expression of these genes and MITF expression across 61 melanoma cell lines in the CCLE database." (PMID 39277608, 2024). "Consistent with that, another study showed that PD-L1 levels positively correlate with MITF expression in melanoma patient biopsies." (PMID 39736644, 2024). "In contrast, MITF has been identified as a positive regulator of PD-L1 in melanocytes and melanoma cells and myeloid-derived suppressor cells." (PMID 39736644, 2024). "The miRNA-182 promotes cell migration and survival in melanoma through the negative regulation of MITF." (PMID 39594467, 2024).
melanoma (continued). "TT-012 suppresses the proliferation of high-MITF melanoma cells and hinders tumor growth, albeit with some damage to liver and immune cells in animal models." (PMID 38534309, 2024). "Similar to miR-211-5p, MITF is also highly expressed in normal melanocytes and has an important function in melanocyte differentiation, whereas in melanoma, similar to miR-211-5p, variable expression of MITF was shown." (PMID 39409187, 2024). "These plasmids were co-transfected in different melanoma cells together with MITF siRNA or scrambled (SCR) sequences." (PMID 38472212, 2024). "Then, PRDX1 expression is similar to MITF in patient melanoma cells, which corroborates our in vitro data using the clones." (PMID 38790661, 2024). "We and other researchers have reported growth inhibition of melanoma cell lines in response to A-485 treatment in an MITF-dependent manner." (PMID 38994683, 2024). "MITF-high melanomas are more proliferative, differentiated, and less invasive than MITF-low melanomas." (PMID 39277608, 2024). "MITF is crucial for the development, advancement, and recurrence of melanoma and is viewed as a potential target for treatment." (PMID 38534309, 2024). "Regarding melanoma motility, AR was previously reported to promote melanoma metastasis via transcriptional upregulation of miRNA-539-3p, which impacts MITF and AXL signaling." (PMID 38326303, 2024). "PGC-1α-positive melanoma cells, a subset of melanomas driven by MITF with high PGC-1α expression, exhibit elevated mitochondrial oxidative phosphorylation and a high energetic state." (PMID 38994987, 2024). "Taking into account the oncogenic role of MITF in malignant melanocytes, this sheds light on the involvement of Rab27 in melanoma." (PMID 39596498, 2024). "MITF genomic amplification promotes melanoma development, and it can facilitate resistance to multiple therapies." (PMID 39277608, 2024). "In the current study, melanoma cell treatment increased the expression of MITF and its downstream genes CDK2, c-Met, Bcl2, and RAB27A." (PMID 39684511, 2024). "In summary, beyond the essential role of MITF in melanoma survival and oncogenesis, we identified an MITF-regulated redox program with multiple new direct and indirect transcriptional targets that eliminate cellular ROS." (PMID 39277608, 2024). "BRAF inhibitors, such as PLX4032, which have been reported to upregulate PGC1α expression in melanomas, inhibit metastasis partly by suppressing the Wnt/β-Catenin-MITF pathway and promoting the expression of PGC1α." (PMID 38774408, 2024). "This article narratively reviews the role of some genetic features related to melanoma formation in horses, such as STX17 mutation, ASIP or MITF alterations, and the link between the graying process and the development of these tumors." (PMID 36670786, 2023). "On study demonstrated that melanoma cells with MITF amplification were more resistant to BRAF inhibition, while cells with MITF loss were more sensitive." (PMID 37504268, 2023). "Expression of MITF can be used as a benchmark to distinguish between different melanoma cell states, most often referred to as proliferative and invasive states, or invasive and non-invasive states." (PMID 36675114, 2023). "MITF has been shown to be the master regulator of not only normal melanocytes but also malignant melanomas." (PMID 37370757, 2023). "In the secretomes of MITF-silenced senescent melanoma cells, E-cadherin was reduced and CCL2 (Chemokine (C-C motif) ligand 2) was significantly increased." (PMID 37174106, 2023). "Together, we posit that the involvement of MITF in melanoma is both multifaceted and intricate, potentially assuming distinct functions contingent on the temporal and spatial context within the tumor environment." (PMID 38065972, 2023). "MITF is a master regulator of melanocyte development, as well as melanoma cell quiescence, progression, survival, proliferation, and invasion, and even DNA damage repair." (PMID 36675114, 2023).
melanoma (continued). "In-vitro studies revealed potential mechanisms for fisetin-mediated regulation of Wnt/β signaling in 451Lu human melanoma cells, including a decline in β-catenin levels, an increase in β-TrCP, and a drop in MITF mRNA and protein levels." (PMID 37565061, 2023). "We confirmed that A-alum-1 significantly suppressed MITF nuclear accumulation in α-MSH-treated cells via ERK activation using an ERK inhibitor, which abolished the A-alum-1-mediated dramatic reduction in nuclear MITF levels in melanoma cells." (PMID 37834109, 2023). "Microphthalmia transcription factor (MITF) is a member of the most important transcriptomic family of melanoma." (PMID 37370757, 2023). "Since TYR, TYRP1, TYRP2, PMEL, and MELAN-A are recognised as melanocyte differentiation antigens (MDAs), inhibition of BRAF V600E increases MDAs expression, through the upregulation of MITF, enhancing melanoma immunogenicity." (PMID 37627054, 2023). "In a panel of melanoma cell lines, we monitored gene expression levels of ligands and receptors previously linked to the SOX10/MITF axis." (PMID 36251678, 2023). "The spotlight on SOX10 intensifies in melanoma, where its impact on crucial factors like MITF and cell migration shapes tumor progression and treatment responses." (PMID 38132479, 2023). "The SAMMSON is located 30 kilobase pairs downstream of MITF, a melanoma-specific transcriptional regulator, whose expression correlates with MITF." (PMID 37445678, 2023). "Abnormal MITF activity can contribute to the onset of several diseases including melanoma, where MITF is an amplified oncogene." (PMID 37752231, 2023). "Noticeably, MITF is not only relevant for melanogenesis, as it exerts numerous functions in melanoma cell homeostasis by modulating proliferation, migration, immunosuppression, and many other cancer hallmarks." (PMID 37898636, 2023). "The role of MITF in melanoma is paradoxical as it is an oncogene but also has properties in suppressing melanoma invasion and metastasis." (PMID 37239381, 2023). "Melanoma cells expressing low levels of MITF correspond to a slow-cycling or pro-invasive state (with similarity to “mesenchymal-like”), whereas higher levels of expression of MITF correlate with a proliferation state." (PMID 36675114, 2023). "While MITF is a melanoma-specific factor, SAMMSON has also been observed to be up-regulated in thyroid cancer and glioblastoma." (PMID 37445678, 2023). "For example, HMB45 and MiTF are expressed in PEComa, along with smooth muscle markers also expressed in dedifferentiated melanomas." (PMID 37373134, 2023). "Lineage-specific transcription factors (TFs), such as SOX10 and MITF in melanoma, have emerged as a common class of essential genes in large-scale functional cancer cell line fitness screens." (PMID 37554444, 2023). "It is well-known that MITF is an important determinant of melanoma cell plasticity and tumor heterogeneity which are undoubtedly one of the main hurdles for the powerful immunotherapy of melanoma." (PMID 37123908, 2023). "Apart from melanoma, subsequent studies have suggested that MITF has multiple effects on cancers such as hepatocellular carcinoma, pancreatic cancer, lung cancer, and papillary renal cell carcinoma." (PMID 36834926, 2023). "In melanoma, one of the melanoma survival oncogenes, MITF, is found to be the driver for the reversible DT state after exposure to BRAF and MEK inhibitors." (PMID 37638338, 2023). "A previous study has demonstrated that AR is important in promoting the proliferation of melanoma by down‐regulating MITF." (PMID 37070131, 2023). "Based on these findings, it can be inferred that acenocoumarol exerts anti-melanogenic effects on melanoma cells by reducing MITF expression via the MAPK signaling pathway." (PMID 37111361, 2023). "Microphthalmia-associated transcription factor (MITF) is a master regulator of key aspects of the biology of melanocytes and melanoma cells, including survival, differentiation, and proliferation." (PMID 37762683, 2023).